LINC01182 (long independently transcribed non-coding RNA 1182)
Synonyms: LINC01085
Gene: Long non-coding RNA gene on chromosome 4 (13,654,295 to 14,254,578, forward strand). Ensembl gene ENSG00000250634.
Diseases named in the same sentence as LINC01182 in open-access papers:
LINC01182 is named in the same sentence as 1 disease in open-access papers, as found by Europe PMC text mining. Sharing a sentence is not in itself a finding about the gene and the disease.
LINC01182 shares sentences with these, for which no sentence is quoted: cancer (1 paper).